MIR4780 (microRNA 4780)
Synonyms: hsa-mir-4780
Gene: MicroRNA gene on chromosome 2 (88,082,519 to 88,082,599, reverse strand). Ensembl gene ENSG00000265003.
Homologues: Orthologues: chimpanzee MIR4780 (100% identical).